RNU1-68P (RNA, U1 small nuclear 68, pseudogene)
Gene: Small nuclear RNA gene on chromosome 1 (149,700,151 to 149,700,296, reverse strand). Ensembl gene ENSG00000275229.
Homologues: Orthologues: chimpanzee U1 (100% identical), macaque U1 (91% identical), dog U1 (71% identical), guinea pig U1 (64% identical). Paralogues in human: RNU1-143P (100% identical), RNU1-153P (100% identical), U1 (100% identical), RNU1-5P (94% identical), U1 (92% identical), RNU1-6P (90% identical), RNU1-1 (75% identical), RNU1-19P (75% identical), RNU1-2 (75% identical), RNU1-27P (75% identical), RNU1-28P (75% identical), RNU1-3 (75% identical), and 134 more.